KRAS (KRas proto-oncogene, GTPase)
Diseases named in the same sentence as KRAS in open-access papers (continued):
Sharing a sentence is not in itself a finding about the gene and the disease.
cancer (continued). "YAP/TAZ activation also plays a crucial role in acquiring drug-induced resistance in BRAF and KRAS mutant cancer cells treated with EGFR/MAPK inhibitors." (PMID 35883668, 2022). "YAP/TAZ facilitate tumorigenesis in Ras-driven cancers, possibly via regulation of overlapping, downstream transcriptional targets, and can act as a surrogate for oncogenic Ras in vitro when KRAS is suppressed in cell lines from a range of cancer types." (PMID 35119068, 2022). "There has been considerable research regarding the relationship of expression levels of ABC transporters with KRAS mutations in cancer cells, while the link between the level of ABC transporters and KRAS inhibitors is poorly understood." (PMID 35281897, 2022). "Previous studies have shown that antisense oligonucleotides (ASO) are an attractive treatment for KRAS-driven human cancers, and therefore deserve further development." (PMID 35922812, 2022). "Morphological changes in AK 192 KRAS mutant cancer cells were observed after treatment with oxidative drugs combination 1 mM DVC and 5 μM ATO but not with ATO or D-VC alone at any of the observed time points." (PMID 36619305, 2022). "We further determined the association between BCL6 expression and survival outcomes of patients with KRAS-mutant cancers (n = 689) using TCGA database." (PMID 36377663, 2022). "An ongoing phase 1–2 study of MRTX849 (adagrasib) in KRAS G12C mutant cancers has shown an objective response rate of 45% in NSCLC patients in a KRYSTAL-1 trial, with a DCR of 96%." (PMID 35267628, 2022). "The median progression-free survival (PFS), or the time between the start of treatment and the onset of cancer, of various KRAS mutations has also been studied, with a median PFS of 15.57 weeks and overall survival (OS) of 18.64 weeks for KRAS G12C." (PMID 36004014, 2022). "Previous studies showed that combination therapy with BA and sorafenib showed a potent and synergistic inhibitory effect on the proliferation of cancer cells such as non-small cell lung cancer (NSCLC), A549, H358, and A427 with different KRAS mutations." (PMID 36077036, 2022). "The heterogeneity of response among KRAS-mutant cancers is a far cry from those seen with other kinase inhibitors in NSCLC, for example." (PMID 36284306, 2022). "There is a late G1 cell cycle Gln checkpoint that is passed by KRas-driven cancer cells leading to S-phase arrest instead of G1 arrest." (PMID 36269753, 2022). "Recent clinical development of KRAS inhibitors has heightened interest in the genomic landscape of KRAS-altered cancers." (PMID 36494601, 2022). "Although oncogenic KRAS is highly prevalent in PanINs, most of these lesions remain low grade and rarely progress to cancer." (PMID 36421339, 2022). "A significant association was observed between PD-L1 expression levels and the three KRAS groups (FDR-P < .0001) when including all cancer types." (PMID 35319967, 2022). "Inhibition of mutant KRAS remains a highly pursued goal in drug discovery efforts for the treatment of human cancers." (PMID 35753348, 2022). "We performed a pan-cancer analysis of KRAS-altered samples from 426,706 adult patients with solid or hematologic malignancies using comprehensive genomic profiling; additional analyses included 62,369 liquid biopsy and 7241 pediatric samples." (PMID 36494601, 2022). "In this study, we used the online tool UALCAN to investigate the DNA methylation of KRAS and its related prognostic values in different cancer types." (PMID 35563733, 2022).
cancer (continued). "Clear examples are missense mutations in classic RAS genes (KRAS, HRAS and NRAS) that underlie the development of approximately 13% of human cancers." (PMID 35120522, 2022). "A cytotoxic action of ascorbates is mediated by a glucose-dependent oxidizing effect that determines a selectivity in killing of highly malignant KRAS-mutant cancer cells." (PMID 36359850, 2022). "As previously reviewed by Desai and colleagues, lipids, polymers, peptides, extracellular vesicles, and inorganic nanoparticles have been reported to be internalized by KRAS mt cancer cells through macropinocytosis." (PMID 35154489, 2022). "With recent evidence for tumors employing loss of heterozygosity of the HLA locus as a common mechanism of immune evasion, our study also presented the incidence of HLA LOH across cancers with frequent KRAS alterations." (PMID 36494601, 2022). "Since FRA1 has been shown to modulate the drug response of KRAS-driven cancer cells, we performed an unbiased drug screening experiment in isogenic models." (PMID 36534167, 2022). "The signaling transduction pathways involved in cancer progression in KRAS mutant cells have also been investigated." (PMID 35705962, 2022). "Much evidence suggests that KRAS-mutant cancers, including lung ACs, are a heterogeneous disease composed of different cellular clones and subclones carrying specific molecular patterns." (PMID 36077640, 2022). "In this study, combining nuclear transport inhibitor selinexor with KRAS G12C inhibitors has resulted in potent antitumor effects in preclinical cancer models." (PMID 35573474, 2022). "RAD51 is reported to be highly expressed in KRAS-mutant cancer cells and is a key component in homologous recombination (HR), a pivotal means to repair double-strand DNA breaks." (PMID 35053550, 2022). "In summary, a variety of drug delivery systems with different physical and chemical properties have been reported to enter KRAS mutant cancer cells through macropinocytosis." (PMID 35154489, 2022). "The mutational analysis determined that genes previously identified in cancers were most commonly observed in the profiled patients with mutations in NRAS, KRAS, JAK2, and CREBBP." (PMID 36497424, 2022). "Extensive efforts to silence KRAS in the past three decades have proven fruitless, and it has been considered an undruggable target of cancer." (PMID 35563733, 2022). "Next, we used a different online source, UALCAN, to examine the expression of KRAS in different cancer types and found comparable results to those obtained from TIMER." (PMID 35563733, 2022). "Here, we discuss the use of a vitamin C (VC) acting in high dose as an oxidative “Trojan horse” agent for KRAS-mutant cancer cells that can be potentiated with another oxidizing drug arsenic trioxide (ATO) to obtain a potent and selective cytotoxic impact." (PMID 36359850, 2022). "The most prevalent KRAS mutation in human cancer is KRASG12D, present in 33% of all cases and the most frequent mutant KRAS allele in PDAC (46%)." (PMID 36383067, 2022). "RAS family proteins, particularly KRAS, play central roles in different stages of cancer development, invasion, propagation, metathesis, and angiogenesis, leading to the formation of solid tumors." (PMID 35409064, 2022). "On the other hand, expression of KRAS4B but not KRAS4A was induced by endoplasmic reticulum (ER) stress, which has been previously identified as a therapeutic target in KRAS mutant cancers." (PMID 36393833, 2022). "KRAS is the most common oncogene in human cancers and has long been considered ‘‘undruggable’’—that is, until recently, when covalent inhibitors that selectively target KRASG12C substitution were developed." (PMID 35053550, 2022). "KRAS is the most frequently mutated isoform within the RAS family and one of the most frequently mutated oncogenes in human cancer accounting for more than one fifth of all human tumors." (PMID 34951114, 2022).
cancer (continued). "In the work presented here, we provide evidence that the increase in mTORC2 (Akt phosphorylation at S473) in response to exogenously supplied OA and de novo synthesis of PA lead to the phosphorylation of ACLY in KRas-driven cancer cells." (PMID 36269753, 2022). "Collectively, we present an alternative strategy to target KRAS-mutant PDAC cancer cells using dextran polymeric conjugation." (PMID 35154474, 2022). "We found that KRAS interacts with several cancer-related genes from the PPI network, but their mechanism needs further study." (PMID 36330448, 2022). "Therapies already in use for treatment of KRAS-mutant cancers such as cetuximab, panitumumab, gefitinib and erlotinib present a big challenge in terms of the way cancers overcome the treatments and develop resistance." (PMID 36359850, 2022). "In agreement, one study has mutated KRAS in a poorly immunogenic CRC cell line that resulted in stimulation of immunity and cancer regression due to the secretion of the cytokine, IL-18." (PMID 36430176, 2022). "Accumulating evidence has suggested that KRAS can regulate PD-L1 expression in other cancers, such as NSCLC." (PMID 35305624, 2022). "Constitutively activated, mutant KRAS continuously stimulates downstream effector signaling and promotes nearly all cancer hallmarks." (PMID 34990404, 2022). "HRAS, NRAS, and KRAS, collectively referred to as oncogenic RAS, are the most frequently mutated driver proto‐oncogenes in cancer; the relationship between oncogenic RAS and ferroptosis is still controversial." (PMID 34878732, 2022). "Encouragingly, recent advances in medicinal chemistry have discovered an allele-specific KRAS(G12C) covalent inhibitor, sotorasib (AMG-510), that showed clinical benefit for cancer patients and was conditionally approved by the FDA in 20211,7–9." (PMID 36224201, 2022). "KRAS mutations present in cancer cells impair hydrolysis of GTP, which results in holding KRAS in a permanently active form." (PMID 35408658, 2022). "Considering that a direct targeting of oncogenic KRAS remains elusive and challenging, an unbalanced redox state of highly malignant KRAS-mutant cancers is an attractive area for therapeutics development." (PMID 36359850, 2022). "Despite decades-long steady efforts, therapeutic targeting of KRAS-mutant cancers has remained an overarching challenge in clinical oncology." (PMID 35039048, 2022). "Next, we investigated the mechanism that KRAS-mutant cancer cells utilize to orchestrate cytotoxic ROS upon NOP56 depletion." (PMID 35039048, 2022). "KRAS mutations impair both the intrinsic and GAP stimulated GTP hydrolysis activity, leading to the hyperactivation of KRAS signaling and ultimately cancer." (PMID 36430338, 2022). "The three RAS oncogenes (HRAS, KRAS and NRAS) are part of the most frequently mutated gene family in human cancer, since over 20% of human cancers harbor mutations in one of the three RAS genes, making them the most prevalent oncogenic drivers." (PMID 35456940, 2022). "Taken together, these data suggested that KRAS/CCL2/IL1B transcripts are overexpressed in human KRAS-mutant cancers and detrimentally affect survival." (PMID 35327394, 2022). "A promising ATO and VC or ATO and D-VC drug combination has to be studied in clinical trials to evaluate efficacy of the drug combination in suppressing KRAS-mutant cancers." (PMID 36359850, 2022). "Nonsynonymous mutations were also identified in 51 additional cancer genes in single primary ileal NETs and metastases, including ALK, DAXX, KRAS, and MEN1." (PMID 35922826, 2022).
cancer (continued). "Orilnc1, KIMAT1, SLCO4A1-AS1, LINC01420, KRAS1P, YWHAE, PART1, MALAT1, PCAT-1, lncRNA-NUTF2P3-001 and TP53TG1 are long non-coding RNAs (lncRNAs) whose interactions with KRAS have been verified in the context of cancer." (PMID 35139853, 2022). "New therapies aim to improve immune surveillance and enhance antitumor immunity by precisely targeting cancer cells harboring oncogenic KRAS." (PMID 35014625, 2022). "The KRAS oncogene has been implicated in various cancers, with up to one-third of RMS cases involving the activation of one of the three RAS isoforms, including K-RAS." (PMID 35174853, 2022). "In HEPG2 and MHC97l cancer cells, overexpression of mir-30a completely blocked the activation of the KRAS proto-oncogene, GTPase (KRAS)/ Raf-1 proto-oncogene, serine/threonine kinase (c-RAF)/MAPK/ERK kinase (MEK)/extracellular regulated kinase (ERK) pathway." (PMID 35246136, 2022). "In cancer cells driven by oncogenic KRAS, genes relevant for G2/M-phases of the cell cycle, like Aurora A kinase, were found to be linked to FRA1 and expose a therapeutic vulnerability." (PMID 36534167, 2022). "The combination of RTK inhibitors together with KRAS inhibition is assumed to have combinatorial or even synergistic drug effects in the corresponding cancer cells." (PMID 35565305, 2022). "KRAS-mut cancers conserved a Ca++ transporter and anion transporter (SLC26A8) thought to be expressed only in sperm." (PMID 36612014, 2022). "An obvious current limitation is the infrequent expression of the KRAS(G12C) mutant in different cancers that allows the use of an irreversible covalent cysteine reactive inhibitor." (PMID 34958800, 2022). "The latest NSCLC guideline 2021 V2 edition issued by the national comprehensive cancer network (NCCN) indicated that genes associated with targeted therapy of NSCLC include EGFR, KRAS, ALK, ROS1, MET, BRAF, RET, and NTRK." (PMID 35227278, 2022). "Overall, oncogenic KRAS signaling initiates molecular events that lead to cancer cell immune evasion." (PMID 35014625, 2022). "Observations in vitro and in vivo at acquired resistance to KRAS G12C inhibitors highlighted that cancer cells develop adaptative strategies to overcome the selective pressure and survive under treatment." (PMID 35251972, 2022). "For example, MYC- and KRAS-driven cancers have been reported to be particularly sensitive to the inhibitors of the key players of lipid and glucose metabolism due to the oncogenic reprogramming of the cellular metabolic pathways." (PMID 36480552, 2022). "In fact, these three types of cancer are the main types of malignancies in which KRAS has been found to be epigenetically modulated by non-coding RNAs." (PMID 35139853, 2022). "KRAS also promotes cancer metastasis and increases resistance to chemotherapy in many cancer types including CRC." (PMID 36326938, 2022). "A more in-depth understanding of these concerns will pave the way for the development of well-tolerated and effective therapies for patients with KRAS-driven cancer." (PMID 35449573, 2022). "A deeper understanding of lncRNA function in KRAS-driven cancers is of major fundamental importance and will provide a valuable clinical tool for the diagnosis, prognosis, and eventual treatment of cancers." (PMID 34489556, 2022). "The development of covalent inhibitors against KRAS G12C represents a major milestone in treatment of RAS-driven cancers, especially in non-small cell lung cancer (NSCLC), where KRAS G12C is one of the most common oncogenic driver." (PMID 35177674, 2022).
cancer (continued). "The metabolic rewiring of cancer cells is partly dependent on mutations in oncogenic driver genes, such as MYC and KRAS." (PMID 36612058, 2022). "It has been demonstrated that downregulation of all KRAS isoforms has lethality to cancer cells with aberrant KRAS signaling, and that there is a large potential therapeutic window for other cell types." (PMID 36011352, 2022). "Evidently, it is likely that the combinations of selinexor and KRAS G12C inhibitors induce cell-cycle arrest in KRAS G12C–mutant cancer cells by downregulating cyclin B1 and CDK4 expression and upregulating the accumulation of TSP Rb in the nucleus." (PMID 35573474, 2022). "In this review, we describe the interaction between KRAS and lncRNAs, miRNAs and circRNAs, particularly in the context of cancer." (PMID 35139853, 2022). "These somatic mutations are missense and affect residues homologous to the cancer‐associated ones mutated in HRAS, KRAS and NRAS." (PMID 36394128, 2022). "In this study, from a pan-cancer perspective, high expression of YAP1 was associated with upregulation of TGF-β signaling, KRAS signaling, Hedgehog signaling, EMT, and androgen response in most cancer types." (PMID 36479120, 2022). "KRAS is an important oncogene in various cancers; mutant KRAS induces an increase in the expression of GLUT1, glycolysis, and mitochondrial respiration." (PMID 35757505, 2022). "We must yet await the actual role that mRNA vaccines will play in the treatment and prevention of KRAS-driven cancers." (PMID 35014625, 2022). "This has led to a good deal of effort being directed towards developing strategies to target KRAS, or its effectors, as a cancer treatment." (PMID 36581205, 2022). "RAS genes (KRAS, HRAS, NRAS) are the most commonly mutated oncogenes in cancers, resulting in increased downstream signaling that drives incessant proliferation and tumorigenesis." (PMID 36531078, 2022). "Consistent with this, we found that EGFR-mut cancers conserved more homeobox genes and genes related to RNA Polymerase II compared to KRAS-mut and NEK cancers." (PMID 36612014, 2022). "KRAS is an especially prevalent contributor to human cancers affecting the pancreas, colon and lung." (PMID 34580712, 2022). "This novel combination therapy can potentially improve treatment outcomes in KRAS G12C–mutant cancers." (PMID 35573474, 2022). "Treatment with this compound reduces the cellular levels of KRAS, leading to the suppression of KRAS-dependent cancer cell growth in vitro and in vivo." (PMID 35546148, 2022). "NanoString nCounter technology was used to analyze gene expression profiling involved in cancer progression in HCT-116 cells (KRAS MT CRC)." (PMID 36005485, 2022). "The synergistic benefit of the combination therapy was consistently observed in different CDX and PDX models of KRAS (G12C) cancers." (PMID 35922812, 2022). "A comprehensive up to date analysis revealed that ~ 19% of cancer patients harbor RAS mutations and over 85% are in KRAS, equivalent to ~ 3.4 million new cases per year worldwide." (PMID 35307764, 2022). "It is worth noting that most of the earlier studies were performed using KRAS oncogenic mutant cancer CRC cell lines." (PMID 34919787, 2022). "We have also revealed a novel synthetic lethality between NOP56 depletion and mTOR inhibitors that occurs by impeding the homeostatic mechanism of ROS in KRAS-mutant cancer cells." (PMID 35039048, 2022). "Among several analogs of VC, only its enantiomer D-VC in combination with ATO showed a similar potent cytotoxic effect in killing KRAS-mutant cancer cells in cell culture." (PMID 36359850, 2022).